CD86 (CD86 molecule)
Diseases named in the same sentence as CD86 in open-access papers (continued):
Sharing a sentence is not in itself a finding about the gene and the disease.
infection (continued). "We previously reported that MP-12 infection significantly increased expression of activation markers CD86 and CD80 on the surface of microglia." (PMID 38392897, 2024). "In contrast, the expression of the CD86 was significantly increased in the cDC and pDC subsets in the E. multilocularis infection group at 24 weeks after infection." (PMID 38787028, 2024). "Our results revealed that the infection of moDC with L. mexicana significantly diminishes CD86 presence, which coincides with previous reports and suggests that L. mexicana is a poor inducer of DC maturation." (PMID 38787051, 2024). "Though we found no change to steady state levels of costimulatory molecules on aged DCs, others have reported that aged murine DCs have reduced upregulation of CD86 in response to infection." (PMID 38481058, 2024). "Cluster analysis revealed the non-uniform distribution of Klebsiella across the different subpopulations of neutrophils predominating the infection of cells PD-L1+ and CD86-." (PMID 38578798, 2024). "After 13 days of supplementation with L. lactis JCM 5805, antiviral response indicators (CD86) increased alongside a reduced number of days where URTI infection symptoms were reported." (PMID 38474848, 2024). "Along the course of infection, there was a reduction in the expression of M1 markers like Nos2, Cd40,Cd86, Tnfa, Nfkb2, Il6 and a corresponding increase in the expression of the M2 markers such as Arg1, Ccl17, Cd206, IL4ra with an exception of Tgfb." (PMID 39693143, 2024). "These two subpopulations were found at 48 and 72 h post infections although the main subpopulation at these time points was cluster 34 (Siglec-H- PD-L1+ CD86-)." (PMID 38578798, 2024). "In our in vitro model, infection by P. aeruginosa induced a marked increase in CD86 expression, and a slight rise in CD206, suggesting a heterogeneous population of macrophages characterized by high plasticity, as observed in other contexts." (PMID 39458645, 2024). "In non-infected mice, more than 90% of the neutrophils correspond to cluster 8 (CD11blow Siglec-H+ PD-L1- CD86+) whereas this subpopulation was significantly reduced in the infected mice, particularly at 48 and 72 h post infection." (PMID 38578798, 2024). "We observed that MVA∆E5R-OVA infection induced higher levels of CD86 and CD40 expression compared with MVA-OVA at 24 h post-infection." (PMID 37217469, 2023). "Switched memory B cells were observed to have higher expression of CD86 compared to unswitched memory B cells in severe infection, whereas unswitched memory B cells displayed higher expression levels of CD21 than switched memory." (PMID 37638016, 2023). "DC infection with 5448AP resulted in significantly reduced expression of MHC II, CD80, and CD86 in comparison to infection with 5448 (P < 0.05 to 0.01) (respectively)." (PMID 36744883, 2023). "The macrophages extracted from the livers of mice infected with C. hepatica expressed high levels of F4/80+CD86+, where the expression reached its peak at 3 weeks post-infection, coincident with the development of adult worms in the liver parenchyma." (PMID 36668953, 2023). "This need for CD80 and CD86 in the pro-inflammatory response to S. aureus was evident early in the infection and in vitro using bone-marrow-derived macrophages." (PMID 37004108, 2023). "In particular, splenic cDC expressed higher levels of CD40, CD80, and CD86 from 4 h to 48 h post-infection compared with 0 h, especially at 4 h, with values of 21.1% ± 5.3 (p = 0.028), 48.1% ± 5.0 (p = 0.018), and 36.2% ± 3.1 (p = 0.009), respectively." (PMID 36977141, 2023). "The flow cytometry revealed that PD-L1 was stimulated on the M1 macrophages (CD86+) at the early stage of infection and reached a peak at the 3rd week of infection." (PMID 36668953, 2023). "While expression of CD80 (B7-1) and PDL1 was continuously upregulated throughout infection, CD86 (B7-2) expression increased initially at D4 but dropped by 0.41-fold at D8." (PMID 37146079, 2023).
infection (continued). "By contrast, CD86 can both enhance and impair immune responses to infection, likely depending on the context." (PMID 36812322, 2023). "And we also investigated the expression of cell-surface markers in splenic MΦs, the results showed that the levels of CD40, CD80 and CD86 both increased significantly at 96 h following i.v infection." (PMID 38012553, 2023). "The expression levels of the M1-like activation markers iNOS, CD80 and CD86 were much higher in SEPT2-deficient PMs upon VSV infection at various time points post-infection and with different multiplicities of infection (MOI)." (PMID 37978190, 2023). "NK-cell depletion significantly reduced the number of CD103+CD11b– DCs expressing CD86 or CD8α following T1L infection, but the frequency of these populations remained unchanged." (PMID 35993365, 2022). "Compared to saline-Fc treated mice, Sema3E-Fc treated WT, and Sema3E KO mice showed higher MHC‐II, CD40, CD80, and CD86 molecules on the surface of DCs following infection." (PMID 35983029, 2022). "The level of CD86 expression in macrophages considerably dropped as infection progressed in a time‐dependent manner, while the amount of CD86 in the supernatant significantly increased." (PMID 36444627, 2022). "Professional hematopoietic APCs upregulate MHCII and costimulatory receptors (CD40, CD80, and CD86) under inflammatory conditions triggered by infection, injury, and/or stress." (PMID 36227687, 2022). "(G) Quantification of median fluorescence values of co-stimulatory molecules (CD40, CD80, and CD86) on WT DCs stimulated with ON (black) or ON after pre-treatment of DCs with 50 mM FK506 for 20 min prior to infection (green)." (PMID 35881547, 2022). "To further confirm the polarization status of macrophage cells during infection, we measured macrophage CD86 and CD206 by flow cytometry." (PMID 36558799, 2022). "In a prior study, it was shown that as infection progressed, CD86 expression levels in macrophages considerably declined while CD86 concentrations in the supernatant significantly increased." (PMID 36444627, 2022). "Lentivirus‐mediated CD86 overexpression in macrophages showed a significant macrophage activation at early stages of infection, while NO and IL‐1β increased significantly showing stronger phagocytosis and killing ability." (PMID 36444627, 2022). "The results showed that the levels of the M1-type membrane molecules CD80 and CD86 were increased on human dMφ after infection with T. gondii, while the levels of the M2-type membrane molecules CD206 and CD163 were decreased." (PMID 36514159, 2022). "An important question that needs to be investigated is the role of CD86 in macrophage infection with T. marneffei?" (PMID 36444627, 2022). "M1-type markers (iNOS, CXCL-10, and CD86) were significantly upregulated after infection, and the expression level of M2-type markers (CD206 and ARG1) did not change significantly." (PMID 36352407, 2022). "The costimulatory molecules, CD80 and CD86, were suppressed due to infection with M. s_Rv1515c, pointing to the role of Rv1515c in dampening the costimulatory signals required for T cell activation." (PMID 35813825, 2022). "Activated macrophage frequency based on co-expression of MHC-II and CD86 was unchanged following infection." (PMID 34436169, 2021). "Surprisingly, despite completely suppressing DC infection, 1% P80 natural essence significantly enhanced CD86 surface expression in HIV-exposed DCs and even slightly increased this marker also in already CD86-high HIV-C-loaded DCs." (PMID 34579213, 2021). "Of note, the P2RY12hiCD86− cells upregulated CD86 during infection, becoming P2RY12hiCD86lo microglia." (PMID 34311763, 2021). "Consistently, down-regulated M2 marker CD206 and up-regulated M1 marker CD86 were observed in siS100A9-transfected Mφ infection with Fn by western blot." (PMID 34093546, 2021).
infection (continued). "The expression of antigen-presenting molecules (e.g., HLA-DR) and co-stimulatory molecules (e.g., CD86) on DCs is important to T cell priming in response to infection." (PMID 34566996, 2021). "Here we used flow cytometry to quantify the induction of Signal 1 (MHC-II) and Signal 2 (CD86) after infection with one pandemic (Cal) and two seasonal (Tx and NC) H1N1 IAV strains." (PMID 34335598, 2021). "DC1 and DC2 responses increase in the lung in modest capacity and DCs overall upregulate MHC-II and CD86 co-expression by day 7 post-infection while macrophages fail to upregulate co-expression, somewhat replicating the in vitro data." (PMID 34436169, 2021). "First, DC isolated from SND1-/- mice exhibited significantly lower CD40/CD80/CD86 expression and IL-12 production, but higher IL-10 production than wild-type mice during Cm infection." (PMID 33635920, 2021). "Splenic SND1-/- DCs showed lower expression of CD40, CD80 and CD86 molecules than splenic wild-type DCs especially at day 7 following infection both in frequency and mean fluorescence intensity." (PMID 33635920, 2021). "BMDCs were activated after infection with both viral vectors, but VLV caused the strongest increase of activation markers such as MHC II and CD86." (PMID 34811393, 2021). "Single-gating analysis shows CD86+ macrophage frequency in the draining lymph node decreases by day 7 post infection." (PMID 34436169, 2021). "Low intensity of signal for CD206 but high signal for CD86 was also confirmed in siS100A9-transfected Mφ infection with Fn by immunofluorescence assay." (PMID 34093546, 2021). "Only CD16+ cDCs were found to increase expression of maturation markers, HLA-DR and CD86, following infections initiated with either sporozoites or iRBCs." (PMID 31900030, 2020). "Resting and IFNγ-treated macrophages were infected with B. cenocepacia and the expression of class I and II MHC molecules, CD80, and CD86 was quantified at 24 h post-infection." (PMID 32873215, 2020). "They showed that monocytes from secondary sites of infection expressed significantly higher CD86 than those from primary sites of infection." (PMID 32784615, 2020). "Expression of CD86 in both male- and female-derived classical monocytes in the blood increased upon infection." (PMID 32651360, 2020). "CD86 expression was also significantly increased 24 h and 48 h after infection with live MAP or KMAP." (PMID 32635236, 2020). "Vehicle- and TC-treated mice showed equivalent increases in M2b (CD86+) macrophages at later time points following infection." (PMID 32849562, 2020). "RAW 264.7 cells were cocultured with H. pylori at various multiplicities of infection (MOIs), and iNOS, CD86, Arg-1, CD206, and HIF-1α expression was detected by Western blot, PCR, and ELISA analyses." (PMID 33376580, 2020). "CD86 was higher expressed on hepatic classical monocytes from testosterone-treaded mice upon infection, whereas the expression of CX3CR1 was only slightly reduced compared to the control group." (PMID 32651360, 2020). "In mock-infected CA mφ, the MFI values of CD86 were 225, and 211 or 268 for the different time points post-infection." (PMID 31134002, 2019). "In mock-infected resting macrophages, the MFI values of CD86 were 252, and 123 or 8 for the different time points post-infection." (PMID 31134002, 2019). "In mock-infected AA mφ, the MFI values of CD86 were 299, and 1118 or 629 for the different time points post-infection." (PMID 31134002, 2019). "In contrast to primary subpatent infection, HLA-DR and CD86 expression were reduced on CD16+ DCs in adults with acute malaria when compared with convalescent controls." (PMID 30239833, 2019). "CD86 expression increased during the early stage of infection and then decreased gradually after 24 h post-infection; however, the expression of the CD206 increased from 12 hpi and continued to 48 hpi, consistent with the real-time PCR results." (PMID 31156641, 2019).
infection (continued). "Macrophages from SFTSV-infected mice showed the down-regulated surface expression of MHC-II and CD86, which showed further downregulation as the infection proceeded, as compared with the mock-infected mice." (PMID 31156641, 2019). "Expression of CD86 in infected AA mφ stayed at high level or even increased further starting at 24 h post-infection (p.i.)." (PMID 31134002, 2019). "The results showed that RHΔrop16 infection induced higher expression of CD86 and CD80 but lower expression of CD206 on the surface of placental macrophages, when compared to the RH WT infection group." (PMID 32082272, 2019). "A higher number of neutrophils (CD11b+Ly6G+), macrophages and activated macrophages (CD11b+F4/80+MHC-II+ and CD11b+F4/80+CD86+) were found in the lungs of mice infected with the ΔzipD mutant when compared with wild-type infection." (PMID 31887136, 2019). "In the male cohort, blood pDCs also exhibited prolonged increases in CD86 expression, a marker of DC activation, during the first week of infection." (PMID 30135445, 2018). "Reinforcing this interpretation, peritoneal macrophages from mice that received EV Y before infection showed less CD86 than did macrophages from mice that received PBS before infection." (PMID 29755471, 2018). "Both CD80 and CD86 were down-regulated on B cells following infection with the SV40 mutant strain 776-2E-SM1." (PMID 29432481, 2018). "At 1, 3 and 7 days following infection, single cell suspensions prepared from freshly digested lung tissue were stained for CD11c, CD86 and MHC II." (PMID 28720115, 2017). "As expected, LPS treatment augmented CD40-postive and CD86-positive CD11c+ DCs as compared to the mock infection." (PMID 28150813, 2017). "The pro-inflammatory mediators (TNF and IL-6) MHC-I/II and B7.2 (CD86) were also up-regulated during infection over time." (PMID 28067803, 2017). "This assay showed that after MCMV infection, the expression of CD86 on pulmonary CD11chiMHC-IIhi cells (encompassing conventional DCs) was higher at 3 days post-infection than at 1 or 7 days post-infection, accompanied by a downregulation of MHC II." (PMID 28720115, 2017). "In this way, it is possible that in these initial interactions, once our experiments were performed after a 24-h infection with Leishmania parasites, these DCs regulate CD86 expression positively, being able to activate naive lymphocytes." (PMID 27536300, 2016). "In contrast, B cell expression of MHC I and CD86 was unaltered at day 3 post infection in RRV-infected NOD.IFNAR1−/− mice." (PMID 27405244, 2016). "To determine macrophage activation under conditions of sustained p55TNFR presence, we analyzed the frequencies of CD11b+MHC-II+ cells as well as the MFIs of cell surface MHC-II, CD80 and CD86 expression on CD11b+ cells in the lungs at 21 days post-infection." (PMID 27995986, 2016). "AmB treatment particularly enhanced the CD80 and CD86 expression up to 53% (P < 0.001) and 22.8% (P < 0.01), respectively with respect to infection control." (PMID 25884649, 2015). "To test the maturation status of NSR infected DCs, we analysed surface expression of MHC-I, MHC-II, CD40, CD80, CD83 and CD86 molecules upon infection." (PMID 26575844, 2015). "With increased time of infection, the expression of M1 macrophage-related markers, including CD86, CXCL11, and TNF-α decreased, while the expression of M2 macrophage-related markers including CD206, CCL17 and IL-10 gradually increased." (PMID 26091535, 2015). "With respect to the immunosuppressive capacity of MSC we observed significantly reduced CD86 surface expression on lung CD103+ DC in MSC-treated animals early after infection." (PMID 26438075, 2015). "Expression of the MHC class II molecule, HLA-DR, was also significantly increased upon infection of MDM with X31 as was CD86." (PMID 25775126, 2015).
infection (continued). "Expression of CD86 in cp BVDV1b TGAC infected Mo-DC was up-regulated from mock-infected controls as 100% at 0 hour to 261.22 ± 162.00 (i.e.160%) at 72 hours post-infection." (PMID 24607146, 2014). "The cp BVDV1b-TGAC strain enhanced MHCI, MHCII, and CD86 expression, while ncp strains of BVDV (i.e., ncp BVDV2a 1373, ncp BVDV2a 28508-5, and ncp BVDV1b TGAN) reduced the MHCI, MHCII, and CD86 expression during the course of infection." (PMID 24607146, 2014). "MDCs showed up-regulations of the maturation markers CD80 and CD86 in blood and LN at early time points of primary infection (in blood: p = 0.008 at day 4 pi for CD86 and p = 0.008 at day 2 pi for CD80, in LNs: p = 0.031 at day 9 for CD80)." (PMID 24991927, 2014). "Specific depletion of Tregs late after infection mimicked the CD86 blockade phenotype, confirming a role for Tregs during recovery after virus clearance." (PMID 25144228, 2014). "CD86 showed a pattern of significantly increasing expression with age at infection, and CD80 showed lower expression in mice infected at or under two weeks old than during adult infection." (PMID 24550729, 2014). "We found that Tregs did express high levels of both CD28 and CTLA4, as well as lower levels of CD86 over the course of infection." (PMID 25144228, 2014). "This was mirrored more explicitly in the MFI of CD86 in the corresponding time points and infection modalities." (PMID 25075973, 2014). "Following infection or mock-infection (i.e., control cells) with the four strains of BVDV, the Mo-DC were stained for MHCI, MHCII, or CD86 and fixed at 0, 1, 6, 12, 24, 48, and 72 hour(s) to determine the effects of infection on cell surface expression." (PMID 24607146, 2014). "CD80/CD86 antibodies had the largest effect on CD8+ T cell responses when administered two days post-infection." (PMID 24550729, 2014). "By detection of CD86 levels on brain MΦs we found that all three modalities of infection displayed a rise in MΦ activation compared to control." (PMID 25075973, 2014). "Flow cytometry analysis of infected cells did not reveal a statistically significant increase in CD40, CD80 and CD86 surface expression in DCs infected with btpB mutant when compared to the wild type at 8 h post-infection." (PMID 23847770, 2013). "After infection, cells were analyzed for the expression of costimulatory molecules (CD86, CD80, and PD-L1), cytokine production, and the ability to stimulate allogenic CD4+ T cell proliferation." (PMID 23829893, 2013). "As expected from previous data, HIV-1 alone was unable to infect DCs and “enforced” infection resulted in high levels of CD86 expression by HIV-1-infected DCs and the secretion of high levels of IFN-γ in the culture supernatant." (PMID 23497283, 2013). "Both BDCA-1+ and BDCA-3+ mDCs were susceptible to infection with RSV and demonstrated enhanced expression of CD86, and the inhibitory costimulatory molecules CD80 and PD-L1." (PMID 23829893, 2013). "Upon EV1-infection, a more pronounced upregulation of CD80 and PDL1 is observed compared to CD86, probably caused by relative high expression of CD86 under unstimulated conditions (mock) that reaches a plateau-phase upon stimulation (EV1)." (PMID 23638101, 2013). "Surface expression of MHC II, CD40, CD80, and CD86 were significantly (p<0.05) up-regulated at 20 h after infection with O. tsutsugamushi, even though the levels of expression were lower than those of cells stimulated with LPS." (PMID 23301113, 2013). "IDO is upmodulated during antigen presentation by the engagement of CTLA-4/B7.1/B7.2 (CD80/CD86) molecules on lymphocytes and human dendritic cells (DCs), in response to infection and tissue inflammation (TNF-α, PGE2, IFN-α/β/γ secretion)." (PMID 23213488, 2012). "CD80 and CD86 expression is muted during chronic infection, similar to what has been observed at early times (∼5 hr) post infection." (PMID 22911108, 2012).